ANGPTL3 (angiopoietin like 3)
Diseases named in the same sentence as ANGPTL3 in open-access papers (continued):
Sharing a sentence is not in itself a finding about the gene and the disease.
familial hypercholesterolemia (continued). "Interestingly, the mean reduction in LDL-C, TG and ANGPTL3 observed in these studies were similar in healthy volunteers and patients with heterozygous familial hypercholesterolemia." (PMID 35459248, 2022). "At least 5 different loci have been associated with rare cases of monogenic FCHL: LDLR16,17, LPL15, APOE34, PCSK935 and APOA536,37, but ANGPTL3 does not appear to be associated with this form of FCHL nor familial hypercholesterolemia (FH)." (PMID 33772079, 2021). "Based on data emerging from various GWA studies on ANGPTL3 and its role in regulating plasma lipid levels, ANGPTL3 has been targeted as a treatment for people with elevated plasma lipids, especially for people diagnosed with homozygous familial hypercholesterolemia." (PMID 34067751, 2021). "ANGPTL3 ASOs and evinacumab could decrease lipid levels both in animal models and in clinical trials in patients affected by homozygous familial hypercholesterolemia." (PMID 34298929, 2021). "The mechanism by which evinacumab, a fully human monoclonal antibody directed against ANGPTL3 (angiopoietin-like 3 protein) lowers plasma LDL (low-density lipoprotein) cholesterol levels in patients with homozygous familial hypercholesterolemia is unknown." (PMID 33691480, 2021). "For example, evinacumab, an antibody that inhibits ANGPTL3 not only reduces TG level in circulation by enhancing LPL activity but also significantly decreases low-density lipoprotein cholesterol (LDL-C) in patients with familial hypercholesterolemia (FH) in two independent phase 3 trials." (PMID 35187136, 2022). "Angiopoietin-like protein 3 (ANGPTL3) is a promising target in lipid-lowering therapy, particularly for patients with familial hypercholesterolemia and other severe lipid disorders." (PMID 41557222, 2026). "New therapies targeting the LPL inhibitors, ApoC‐III and ANGPTL3, have recently been trialled in adults with FCS and homozygous familial hypercholesterolemia, respectively." (PMID 38974610, 2024). "The ANGPTL3/8 complex inhibits LPL 100-fold more potently and circulates at much lower levels than ANGPTL3 alone, making it an interesting potential therapeutic target for the treatment of HTG and hypercholesterolemia." (PMID 37642858, 2023). "More recently, evinacumab, an inhibitor of angiopoietin-like 3 (ANGPTL3), has shown the capacity to reduce LDLc significantly, even in homozygotes for familial hypercholesterolemia." (PMID 36904248, 2023). "Evinacumab is an ANGPTL3 inhibitor that has been approved by the FDA for the treatment of adult and pediatric patients aged 12 years and older with homozygous FH, refractory hypercholesterolemia, and severe hypertriglyceridemia." (PMID 36839781, 2023). "The first drug in the class of ANGPTL3 inhibitors is evinacumab, a monoclonal antibody already approved by the FDA and EMA for the treatment of familial hypercholesterolemia." (PMID 35890138, 2022). "The monoclonal antibody against ANGPTL3, evinacumab, has been shown to reduce LDL-C by approximately 50% in individuals with homozygous familial hypercholesterolemia on maximally tolerated lipid-lowering therapy." (PMID 35956226, 2022). "The newest possibilities for the treatment of dyslipidaemia are ANGPTL3 inhibitors with evinacumab, already approved by the FDA, and EMA for the treatment of familial hypercholesterolemia." (PMID 35890138, 2022).
familial hypercholesterolemia (continued). "The ANGPTL3 monoclonal antibody, evinacumab, was reported to reduce plasma TG and LDL-C levels in healthy subjects and patients with homozygous familial hypercholesterolemia." (PMID 31843957, 2020). "Monoclonal antibodies and/or antisense therapy directed against PCSK9 and ANGPTL3 are FDA approved in other indications than cancers (cardiovascular disease, familial hypercholesterolemia), while inhibitors of Lp(a) are currently investigated in clinical trials (ex: Phase 3 trial NCT04023552)." (PMID 36203122, 2022). "By targeting circulating ANGPTL3, everolimus has been shown to effectively reduce levels of low-density lipoprotein cholesterol (LDL-C), high-density lipoprotein cholesterol (HDL-C), and TG in both healthy individuals and patients with familial hypercholesterolemia." (PMID 40559376, 2025). "In addition, the FDA recently approved evinacumab (trade name Evkeeza), a monoclonal antibody against human ANGPTL3, following phase III clinical trial results demonstrating impressive (49%) reduction in circulating LDL in patients with severe, inherited forms of hypercholesterolemia." (PMID 35289308, 2022). "Furthermore, in HeFH patients and non familial hypercholesterolemia patients with refractory hypercholesterolemia, repeated dosing with ARO-ANG3 significantly reduced mean ANGPTL3 levels between 62 and 92%, LDL-C between 23 and 37%, and triglycerides between 25 and 43%." (PMID 34581310, 2021).
atherosclerosis (49 papers, 2016 to 2025). A disease characterized by the build-up of fatty material and calcium deposition in the arterial wall resulting in partial or complete occlusion of the arterial lumen. "Deletion of the ANGPTL3 gene in ApoE-deficient mice has been reported to reduce the development of atherosclerosis." (PMID 40503438, 2025). "It is also linked to atherosclerosis and the levels of ANGPTL-3 and their relationship with lipid and glucose metabolic markers in patients recently diagnosed with T2DM." (PMID 41026696, 2025). "ANGPTL3 is a new therapeutic target for atherosclerosis and inhibition of ANGPTL3 can reduce the residual cardiovascular risk." (PMID 29940978, 2018). "Angptl3 deletion was also reported to reduce the development of atherosclerosis in apolipoprotein E (apoE)-deficient mice." (PMID 29440457, 2018). "When the region including Angptl3 LOF was introduced to atherogenic apoE-knock out mice, the prevalence of atherosclerotic lesions significantly declined indicating that ANGPTL3-deficiency and the resulting hypolipidemia in these mice, was protective against the development of atherosclerosis." (PMID 26754661, 2016). "Therefore, high levels of ANGPTL3 may be associated with atherosclerosis progression and adverse cardiovascular events, including MI and stroke." (PMID 39728292, 2024). "Loss of function mutations in ANGPTL3 also correlate with decreased risk of ASCVD in epidemiological studies, while inhibition of ANGPTL3 in atherosclerosis-prone mice with the fully human IgG4 monoclonal antibody evinacumab was associated with reductions in atherosclerotic lesions." (PMID 39751968, 2025). "Large-scale genetic studies have further confirmed the importance of ANGPTL3 in lipid metabolism and the development of atherosclerosis." (PMID 41561063, 2025). "Nonetheless, new triglyceride-lowering treatments targeting angiopoietin-like 3 (lipoprotein lipase inhibitor) and apolipoprotein C3 antisense will add further insights into the role of triglycerides in the progression of atherosclerosis." (PMID 38667744, 2024). "We provide the proof of concept that liver-targeted anti-Angptl4 ASO treatment strongly attenuates hyperlipidemia and atherosclerosis development, and combined Angptl3/4 silencing has added lipid-lowering benefit." (PMID 39259836, 2024). "SIRI and ANGPTL3 were consistently identified as top predictors, highlighting their importance in early atherosclerosis detection." (PMID 39459610, 2024). "This study aims to compare the therapeutic potential of liver-specific Angptl3 and Angptl4 silencing to attenuate hyperlipidemia and atherosclerosis development in APOE*3-Leiden.CETP mice, a well-established humanized model for lipoprotein metabolism." (PMID 39259836, 2024). "Since short-term liver-targeted Angptl3 and Angptl4 silencing potently attenuated hyperlipidemia, we next assessed to what extent these treatments would also reduce atherosclerosis development over a treatment period of 12 weeks." (PMID 39259836, 2024). "Logistic regression indicated that SIRI and ANGPTL3 were the most significant predictors of atherosclerosis presence." (PMID 39459610, 2024). "In this mouse model of lipid-driven atherosclerosis development, the reduced atherosclerotic lesion formation was primarily a function of the reduced plasma lipid levels following Angptl3 and Angptl4 silencing." (PMID 39259836, 2024). "Logistic regression identified SIRI and ANGPTL3 as significant predictors of atherosclerosis, with the model demonstrating high accuracy (77%) and sensitivity (93%)." (PMID 39459610, 2024). "Studies assessing agents targeting angiopoietin-like 3 (lipoprotein lipase inhibitor) and apolipoprotein C3 antisense will add further insights into the role of triglycerides in atherosclerosis." (PMID 38667744, 2024).
atherosclerosis (continued). "Using the exome sequencing, two nonsense mutations in two patients with familial hypobetalipoproteinemia were identified, revealing the potential role of ANGPTL3 in lipid metabolism and atherosclerosis." (PMID 35548442, 2022). "The impact of ANGPTL3 was further studied in a mouse model of atherosclerosis (ApoE−/− background), where the Angptl3−/− resulted in a significant reduction in the atherosclerotic lesions." (PMID 34356847, 2021). "Pharmacologic antagonism of ANGPTL3 with a human monoclonal antibody was found to greatly diminish plasma lipid levels and atherosclerosis, which is comparable to that reported previously in the same mouse model treated with atorvastatin." (PMID 34829992, 2021). "The preclinical studies indicated that suppression of hepatic Angptl3 protein production in mice resulted in reduced liver triglyceride content, enhanced insulin sensitivity, and limited atherosclerosis progression." (PMID 34829992, 2021). "Increasing age, sex, higher body mass index, smoking, diabetes, hypertension, elevated ANGPTL3 and decreased ANGPTL4 had a statistically significant association with atherosclerosis development in the univariable analysis." (PMID 34742313, 2021). "Animal studies have shown that deletion of Angptl3 can reduce atherosclerosis development in apolipoprotein E knockout mice." (PMID 32280540, 2020). "ANGPTL3 induced angiogenesis with a magnitude comparable to vascular endothelial growth factor-A, which promotes intimal thickening and induces atherosclerosis." (PMID 32280540, 2020). "Consistent with this notion, a recent publication revealed that triple combination treatments of statins and antibodies targeting PCSK9 and ANGPTL3 yielded additive effects on cholesterol and atherosclerosis reductions in mice." (PMID 32646941, 2020). "Another research group showed that treating mice and human subjects with antisense oligonucleotides targeting Angptl3 messenger RNA reduced atherogenic lipoproteins and retarded the progression of atherosclerosis." (PMID 29440457, 2018). "A decreased expression of ANGPTL3 in apolipoprotein E (apoE)-null mice is protective in the development of atherosclerosis." (PMID 30011918, 2018). "The finding by Camenish and collaborators that ANGPTL3 promotes angiogenesis by binding αVβ3 highlighted once more the importance of ANGPTL3 in atherosclerosis, in which neo-angiogenesis is one of the main hallmarks." (PMID 30011918, 2018). "Hepatic Angptl3 silencing similarly attenuated hyperlipidemia and atherosclerosis development." (PMID 39259836, 2024). "In this study, where the degree of Angptl4 silencing was larger than that of Angptl3, Angptl4 silencing consequently induced a greater attenuation of atherosclerosis development than Angptl3 silencing, while the effects of Angptl4 and combined Angptl3/4 silencing were comparable." (PMID 39259836, 2024). "Our data point towards several potential mechanisms through which hepatic Angptl4 silencing may attenuate hyperlipidaemia, and accordingly atherosclerosis development, which only partly overlap with those of Angptl3 silencing." (PMID 39259836, 2024). "In these mice, ANGPTL3 ASO also slowed down the progression of atherosclerosis." (PMID 34581310, 2021). "Increased ANGPTL3 and decreased ANGPTL4 were positively associated with the progression of atherosclerosis, and ANGPTL3 had negative associations with ANGPTL4." (PMID 34742313, 2021). "ANGPTL3, ANGPTL4 and smoking status had a statistically significant association with atherosclerosis in both the univariate and multivariate analyses, but the levels of ANGPTL3 and ANGPTL4 were not different between smokers and nonsmokers." (PMID 34742313, 2021). "ANGPTL3 may promote the development of atherosclerosis and ANGPTL4 may protect against atherosclerosis." (PMID 34742313, 2021).
atherosclerosis (continued). "miRNA-27b may play a role in plasma lipid regulation through genes such as angiopoietin-like-3 and glycerol-3-phosphate acyltransferase-1; its expression was altered in the presence of hyperlipidaemia and atherosclerosis in a murine model." (PMID 33008044, 2020). "All these studies indicate that ANGPTL3 is significantly associated with atherosclerosis and is independent of plasma lipid levels." (PMID 32280540, 2020). "In vivo, reduced ANGPTL3 expression reduced atherosclerosis." (PMID 31772685, 2019). "In addition, emerging evidence supports a possible role of ANGPTL3 in the progression of atherosclerosis through a lipid-independent mechanism." (PMID 30011918, 2018). "Secondly, these large studies used the animal models to investigate the process of atherosclerosis, but the effect of ANGPTL3 in preventing the process of atherosclerosis in humans remains unclear." (PMID 29334984, 2018). "Even though low HDL is an established risk factor for atherosclerosis, decreased HDL levels did not result in accelerated atherosclerosis in ANGPTL3-deficient subjects, probably because of the lifelong exposure to low levels of VLDL and LDL." (PMID 26754661, 2016). "ANGPTL3 has potential atherogenic properties and could directly promote atherosclerosis in humans." (PMID 32280540, 2020). "Feature importance analysis using Random Forest and Gradient Boosting models confirmed the significance of SIRI and ANGPTL3, as well as traditional lipid biomarkers (LDL-C, TC, HDL-C) in predicting atherosclerosis." (PMID 39459610, 2024). "The top predictors of early atherosclerosis identified in our Random Forest feature importance analysis were SIRI, NLR, TC, ANGPTL3, and HDL-C." (PMID 39459610, 2024). "The pharmacological inhibition of ANGPTL3 with monoclonal antibodies shows their safety and efficacy in lowering both LDL-C and triglycerides, thus slowing atherosclerosis progression." (PMID 39728292, 2024). "We analyzed, therefore, changes in circulating ANGPTL3 and ANGPTL4 in obese patients with different metabolic phenotypes and their relation with impaired vasodilator reactivity, an early abnormality in atherosclerosis." (PMID 34440242, 2021). "Most study focus on variation and expression of ANGPTL3 or ANGPTL4 in CHD and AMI, less in atherosclerosis." (PMID 34742313, 2021). "The roles of ANGPTL3 are mostly focused on acute myocardial infarction (AMI), rarely in atherosclerosis." (PMID 34742313, 2021). "Hence, ANGPTL3 may have a promotive effect on atherosclerosis." (PMID 31772685, 2019). "Angiopoietin Like protein 3 (ANGPTL3) is at present considered as a central molecular target for therapy designed to reduce atherogenic lipids and atherosclerosis." (PMID 30086775, 2018). "Besides this last one and PCSK9 inhibitors, also IONIS-ANGPTL3-LRX (target: hepatic ANGPTL3 mRNA; NCT02709850) and AKCEA-APOCIII-LRX (target: hepatic APOC3 mRNA; NCT02709850) are in development in the atherosclerosis field." (PMID 36505351, 2022). "ANGPTL3 is exclusively expressed in the human and mouse liver, and ANGPTL3 deletion in mice leads to increased post-heparin plasma LPL and endothelial lipase activity, reduced levels of circulating TGs and LDL, and reduced atherosclerosis." (PMID 35289308, 2022). "All these results suggested that ANGPTL3 and ANGPTL4 were better risk predictors of atherosclerosis independent of lipids, smoking, and other CHD risk factors that we studied." (PMID 34742313, 2021). "We investigated the role of ANGPTL3 and ANGPTL4 in atherosclerosis development and determined whether plasma concentrations of ANGPTL3 and ANGPTL4 are related to the degree of coronary stenosis." (PMID 34742313, 2021). "In recent years, ANGPTL3 has emerged as a promising target for ASCVD based on observations from preclinical and clinical studies demonstrating that inhibition of ANGPTL3 can lower proatherogenic lipids and in animal models reduce atherosclerosis." (PMID 34371033, 2021).